TLR2 (toll like receptor 2)
Diseases named in the same sentence as TLR2 in open-access papers (continued):
Sharing a sentence is not in itself a finding about the gene and the disease.
tumor (continued). "Therefore, our results support the notion that HA promotes tumor progression mediated by other receptors such as the receptor for HA-mediated motility (RHAMM), lymphatic vessel endothelial receptors (LYVE-1), and toll-like receptors 2 (TLR2) and 4 (TLR4) in canine mammary tumor." (PMID 23426189, 2013). "lactis V9 harmonizes pro- and anti-inflammatory responses through TLR2/TLR4-NF-κB/MAPK signaling, remodels the tumor microenvironment, and enhances αPD-1 efficacy without increasing toxicity." (PMID 42273689, 2026). "The prophylactic effect of TRP2-MITO was validated in the B16-F10 tumor model, and TRP2-MITO did not exert an antitumorigenic effect when used to treat TLR2−/− mice." (PMID 39164536, 2024). "In our study, the absence of TLR2 impaired the proliferation and invasion of HPSCC cells, while TLR2 was elevated in HPSCC tumor tissue, and a high TLR2 level was indicative of poor clinical outcomes for HPSCC." (PMID 37612282, 2023). "No such anti-tumor effect was observed in TLR2-knockout mice treated with HP-NAP, indicating that the TLR2-mediated signaling pathway is required for HP-NAP-induced responses." (PMID 36613542, 2022). "The authors reported efficient tumor elimination at effector:target ratios of 1:10 (TLR2 and TLR4 MOTO-CARs), 1:5 (TLR4 MOTO-CAR), and 2:1 (TLR2 and TLR4 MOTO-CARs), compared to non-transfected macrophages (mock) controls." (PMID 35884798, 2022). "In summary, the expression of Tlr2 and Tlr4 in the TME is important for the promotion of tumor growth, and when both of these receptors are absent, growth is compromised." (PMID 34032639, 2021). "It was observed that MIP therapy reduced tumor burden in wild-type and TLR4−/− mice but not in TLR2−/− mice." (PMID 31590685, 2019). "Co-staining of TLR2, -4, and -9 with the epithelial marker EpCAM clearly indicated TLR expressing tumor cells in primary tumor tissue of all UICC stages (data not shown)." (PMID 27941651, 2016). "At present, little is known about the role of TLR2 and TLR5 in MCL, although their expression has been frequently reported to exhibit tumor-promoting signaling rather than antitumor responses." (PMID 27123851, 2016). "We recently developed rlipo-E7m, which possesses TLR2 agonist activity and robust CD8-mediated anti-tumor activity against palpable tumors in the absence of exogenous adjuvants." (PMID 24642245, 2014). "This indicated that TLR2 and TLR4 were present mainly in the tumor-infiltrating inflammatory cells, not in cancerous tissues." (PMID 25547486, 2014). "The ethanol-treated and untreated tumor cells (PANC/Mock and PANC/TGF-β) showed sustained expression of HLA-ABC, HLA-A2, MUC1, TLR2, and TLR4, but not HLA-DR, CD80, CD86, and CD83 (data not shown)." (PMID 23717436, 2013). "The proliferation of PY8119 cells in vitro was not enhanced by TLR2−/− M2 BMDM and could not be inhibited by PepO-primed TLR2−/− M2 BMDM, while TLR4−/− M2 BMDM promoted tumor cell proliferation and this could be inhibited by PepO reprograming." (PMID 37925462, 2023). "Although we have shown that TLR2 regulates a pro-inflammatory SASP in OIS, it is not yet known whether this has a role in tumor suppression." (PMID 36351380, 2022). "In an in vitro cell model or in vivo tumor tissues, dipyridamole treatment resulted in a decline in the levels of HMGB1, RAGE, β-catenin, Runx2, YAP1, phosphorylated Smad2/3, and cyclin D1, but not TLR2 and TLR4." (PMID 33669632, 2021). "Although TLRs, including TLR2, are expressed in mucosal epithelia and are overexpressed or genetically altered in numerous tumor types, a mechanistic link between TLR activation and evasion of anti-tumor immunity has not been thoroughly explored." (PMID 34638266, 2021). "However, we did not observe induction of TLR2/4, nor NFΚB1/2 suggesting if SAA is promoting atrophy in tumor‐bearing mice it is likely not via TLR signaling." (PMID 33063952, 2020).
tumor (continued). "Since there were no additive effects by inhibition of both TLR2 and TLR4, it was suggested that one of these TLRs may be sufficient for tumour cells to utilize biglycan." (PMID 27295191, 2016). "2.5 × 104 of CD8+ T cells from peripheral bloods of NC (n = 9), peripheral bloods of GC patients (n = 11), and tumor-residency of GC patients (n = 11) were cultured for 12 h in the presence of anti-CD3/CD28 with or without Pam3Csk4, a TLR2 agonist which was used for TLR2 activation." (PMID 34620075, 2021). "The expression of TLR2 is very low or absent on T cells but abundant on several myeloid cells, which suggests that AV-SLPHPV may have a direct effect on myeloid populations in the tumor area besides the induction of specific T cells via APCs in lymphoid organs." (PMID 30541631, 2018).
cancer (271 papers, 2007 to 2026). A tumor composed of atypical neoplastic, often pleomorphic cells that invade other tissues. "As a result of their analyses, the researchers concluded that elevated TLR2 expression is associated with an increase in the growth of cancer cells, which affects the worse prognosis of patients, which confirms the results obtained by our team findings." (PMID 36982898, 2023). "Mara Brancaccio (University of Torino, Italy) recently discovered that Morgana is released from cancer cells and in association with extracellular Hsp90 induces cancer cell migration via Toll-like receptors TLR2, TLR4 and LRP1." (PMID 36602710, 2023). "Among them, increasing expression levels of TLR2, 4, 5, and 9 have been reported to be associated with cancer progression from normal gastric mucosa to pre-cancerous lesions, gastric dysplasia, and ultimately to gastric adenocarcinoma." (PMID 37822929, 2023). "One observational study suggested that Fusobacterium, which was found in much higher levels in cancerous tissue as compared to control tissue, increases cancer risk by increasing inflammatory mediators through a possible miRNA-mediated activation of TLR2/TLR4." (PMID 35807903, 2022). "The Actinomyces in CRC was co-localized with cancer-associated fibroblasts and activated the TLR2/NF-κB pathway and reduces CD8+ T lymphocyte infiltration in CRC microenvironment." (PMID 36119074, 2022). "One of the phagocytosis-associated genes, TLR2 encodes Toll-like receptor 2, which is involved in the release of inflammatory cytokines and facilitation of cancer invasion and metastasis." (PMID 32679794, 2020). "Relationship between Toll-like receptor-2 (TLR2) and cancer risk has been illustrated in some studies, but their conclusions are inconsistent." (PMID 31710083, 2019). "We used STATA to calculate the odds ratio (OR) and 95% confidence interval (95% CI) to evaluate the relationship between certain polymorphism of TLR2 and cancer risk." (PMID 31710083, 2019). "And our meta-analysis combines many types of cancers to study the relationship between TLR2 polymorphism and cancer risk as comprehensively as possible." (PMID 31710083, 2019). "And we also clearly observe that ‘ethnic’ factors are critical in assessing the role of TLR2 in cancer risk." (PMID 31710083, 2019). "We demonstrated both in vivo and in vitro that miR-143 causes TLR2 down-regulation and subsequently inhibits cancer cell invasion and migration." (PMID 23866094, 2013). "In stratified analysis, we found the effect of TLR2 −196 to −174 del on cancer risk remained significant in the subgroup of Caucasians and South Asians, but not in East Asians." (PMID 24376595, 2013). "Growing evidence suggests that mutations of TLR2/TLR9 gene are associated with the progress of cancers." (PMID 22309608, 2012). "Cancer exosomes expressing Hsp72 also stimulate toll-like receptor 2 (TLR2) on MDSC, causing increased MDSC-mediated immune suppressive activity against T cells in vitro." (PMID 22738135, 2012). "Cancer cell TLR2 activation by peptidoglycan of pathogenic bacterium Staphylococcus aureus resulted in enhancement of invasiveness and adhesiveness." (PMID 20520770, 2010). "While the TLRs are primarily known for pro-inflammatory functions, our study identified the engagement of TLR2 receptors by cancer-secreted Hsp70 triggers anti-inflammatory MΦ M2 polarization through the induction of MerTK receptors on MΦs, followed by the association of Hsp70, TLR2, and MerTK." (PMID 39941817, 2025). "TLR2, a crucial receptor in innate immunity, recognizes pathogens and initiates inflammatory responses, thereby playing a significant role in immune regulation and being closely associated with cancer development." (PMID 41515956, 2025). "In addition, the upregulation of TLR4 and TLR2 was found to be positively associated with increases in PD-L1 or PD-L2 in infection and cancer." (PMID 36131933, 2022).
cancer (continued). "Currently, accumulating evidence suggests that TLR2 is closely associated with cancer progression." (PMID 36117156, 2022). "Therefore, we suggest that these anti-cancer therapies would benefit from the association with drugs able to inhibit TLR2 signaling and prevent its pro-tumoral activities." (PMID 33321934, 2020). "For assessing the real influence of TLR2 on cancer risk, we collected more samples than before." (PMID 31710083, 2019). "Elevated expression of TLR2 in our cancer patient group could be associated with invasive or migratory activity." (PMID 23866094, 2013). "A dataset composed of 14627 cases and 17438 controls from 34 publications were included in a meta-analysis to evaluate the association between overall cancer risk or cancer-specific risk and three SNPs of TLRs (TLR2 −196 to −174 del, TLR4 rs4986790 and rs4986791)." (PMID 24376595, 2013). "In addition, functional annotation analysis derived from RNAseq indicates that the highest number of DEGs is linked to neuroactive ligand-receptor interactions, cancer, and calcium signaling pathways, the processes with documented roles of both gangliosides and TLR2." (PMID 41353292, 2025). "Moreover, nonsense mutations in the TLR2 gene that lead to the production of constitutively active truncated forms have been observed, although they are rare, and an increased risk of developing cancer is associated to some TLR2 single-nucleotide polymorphism (SNPs)." (PMID 33321934, 2020). "Therefore, these anti-inflammatory and antiapoptotic properties of quercetin have a key role in the reduction of cancer by controlling the toll-like receptor-2 (TLR2) and JAK2/STAT3 pathway and causing the inhibition of STAT3 tyrosine phosphorylation within inflammatory cells." (PMID 27589790, 2016). "However, population studies showed that TLR2 −196 to −174 del polymorphism might play conflicting roles for the risk of different types of cancer." (PMID 24376595, 2013). "CSPG4, xCT, and TLR2 participate in multiple cancer hallmarks and influence diverse aspects of OSA biology through distinct mechanisms, contributing to OSA pathogenesis and progression." (PMID 41375047, 2025). "This link positions TLR2 not only as an immune-modulatory receptor but also as an upstream regulator of metabolic survival pathways in cancer, possibly also in OSA." (PMID 41375047, 2025). "Flow cytometry was first used to examine the expression of TLR2/4 on MDSCs in peripheral blood of patients with benign or malignant tumors." (PMID 41029721, 2025). "TNF-α secretion by myeloid cells is induced by the activation of TLR2:TLR6 complexes by cancer-secreted vesicles, thereby promoting the growth of metastatic tumors." (PMID 40443670, 2025). "C. albicans can also influence the TLR2/MyD88 and TLR2/NF-κB signaling pathways to upregulate the expression of the programmed death-ligand 1 [PD-L1] with the ability to inactivate cancer cell killer T lymphocytes." (PMID 40258837, 2025). "Here, we tested this possibility using UNE-C1, an immune activator via TLR2/6, by coupling it to a cancer antigen derived from human papilloma virus type 16 (HPV-16) via a designed peptide linker." (PMID 39066478, 2024). "Our findings indicate that sensitivity to UNE-C1-induced cell death is dependent on the expression levels of TLR2 and the Fas-associated death domain (FADD) in cancer cells." (PMID 39669578, 2024). "Toll-like receptors, TLR-4 and TLR-2 are present on a variety of immune cells i.e. NK cells, macrophages and some cancer cells." (PMID 39050853, 2024). "TLR-2 is involved in the pathogenesis of many diseases, including infectious diseases, inflammation, cancer, and autoimmune diseases." (PMID 39201739, 2024). "Cancer cells with attenuated proliferation expressing accumulated TLR2 and TRL9 intrabodies demonstrated reduced STAT3 phosphorylation signaling, while apoptotic markers Caspases 3 and 8 were upregulated." (PMID 38390872, 2024).
cancer (continued). "The intratumoral delivery of TLR2/3 agonists has been shown to induce ICD in cancer cells, highlighting the potential efficacy of this approach." (PMID 39669578, 2024). "For instance, TLR7 and TLR9 are often activated in therapies against viral infections and as adjuvants in cancer vaccines, while TLR2 and TLR4 are targeted by antagonists to mitigate inflammatory responses in sepsis and other inflammatory diseases." (PMID 38732254, 2024). "Briefly, enhancement of cancer cell proliferation, establishment of a cancer‐promoting immune environment through miRNA‐mediated activation of TLR2/TLR4, and the evasion of immune checkpoints have been proposed as its main mechanisms." (PMID 38775019, 2024). "For instance, the incorporation of the Toll-like receptor 2/6 agonist Pam2Cys has been found to enhance the anti-cancer effects of mRNA vaccines and establish a Pam2Cys-dependent long-lasting immune memory." (PMID 38523155, 2024). "Overall, these outcomes strongly suggest that UNE-C1 triggers ICD in human cancer cells through a mechanism dependent on TLR2 activation, with the expression levels of TLR2 and FADD being critical determinants of this process." (PMID 39669578, 2024). "Studies have shown that TLR2, 4 and 9 are the three most important receptors that regulate the progression of various cancers among the TLR receptors (TLR1-10)." (PMID 37153547, 2023). "Tregs, MDSCs, neutrophils and macrophages express TLR2, and upon its activation, they contribute to cancer progression and metastasis due to their immunosuppressive functions." (PMID 38203626, 2023). "TLR2-mediated EMT allows cancer cells to acquire a more migratory and invasive phenotype, facilitating their dissemination to distant sites and the formation of metastasis." (PMID 38203626, 2023). "Further mechanistic understanding of TLR2-induced cancer cell biology and apoptosis inhibition in cellular regulation will enable the identification of novel therapeutic targets." (PMID 37612282, 2023). "Many cancer cell types express TLR2 and take advantage on the activation of its signaling pathway, as will be discussed in the following paragraph." (PMID 38203626, 2023). "These molecules can be actively secreted by cancer cells or passively released during chemo- or radiotherapy, activating TLR2 signaling in either cancer or immune cells." (PMID 38203626, 2023). "TLR2 promotes cancer cell survival and proliferation in breast and gastric cancers, as well as in pancreatic ductal adenocarcinoma." (PMID 38203626, 2023). "Recently, many studies have found that aberrant expression and regulation of TLR2,4,7,9 can promote immune escape and angiogenesis of cancer cells." (PMID 37005579, 2023). "Previous studies have demonstrated that TLR2/YAP axis regulated cancer innate immunity, yet the function of TLR2/YAP axis in macrophages was unclear." (PMID 37464382, 2023). "The secretion of the HSP90 cochaperone protein Morgana induces cancer cell migration by activating TLR2, TLR4, and LRP1." (PMID 38052785, 2023). "Compared with other molecules in the TLR family, TLR4 is relatively highly expressed at the transcriptome level in pan-cancer studies, close behind TLR2." (PMID 35801728, 2022). "It was obvious that TLR2 was highly expressed in most types of cancer, and TLR family members were least expressed in LUSC and LUAD." (PMID 35937402, 2022). "In agreement with our concept, TLR2 was reported to initiate the innate and sustained adaptive immune responses in cancer." (PMID 36389789, 2022). "The association between TLR2 and TLR4 has been shown to correspond with a higher risk of several cancer types." (PMID 36389785, 2022). "We analyzed TLR2 expression in human LUAD samples from The Cancer Genome Atlas (TCGA) (Cancer Genome Atlas Research, 2014 and found that high TLR2 expression significantly correlated with improved survival." (PMID 36351380, 2022).